PP2D1 (protein phosphatase 2C like domain containing 1)
Synonyms: C3orf48; FLJ25449
Tractability: No criterion of Open Targets' tractability assessment is met for any kind of drug.
Gene: Protein-coding gene on chromosome 3 (19,979,961 to 20,012,267, reverse strand). Ensembl gene ENSG00000183977.
Subcellular location (Human Protein Atlas): Nucleoplasm; Intermediate filaments
Gene Ontology:
Molecular function: protein serine/threonine phosphatase activity
Biological process: negative regulation of MAPK cascade
Cellular component: cytoplasm; nucleus
Genetic constraint (gnomAD): Loss-of-function variants: 23 observed, 26.82 expected, observed/expected ratio (o/e) 0.86, 90% interval 0.62 to 1.22. The upper end of that interval is the gene's LOEUF score, 1.22, which puts it in group 5 of 6, group 1 being the genes least tolerant of losing a copy. Missense variants: 741 observed, 739.36 expected, observed/expected ratio (o/e) 1, 90% interval 0.94 to 1.07. Synonymous variants: 252 observed, 260.26 expected, observed/expected ratio (o/e) 0.97, 90% interval 0.87 to 1.08.
Homologues: Orthologues: chimpanzee PP2D1 (99% identical), macaque PP2D1 (95% identical), pig PP2D1 (70% identical), dog PP2D1 (70% identical), rabbit PP2D1 (67% identical), rat Pp2d1 (56% identical), mouse Pp2d1 (56% identical), tropical clawed frog pp2d1 (29% identical), Drosophila melanogaster CG10376 (12% identical), Drosophila melanogaster CG17746 (11% identical), Drosophila melanogaster alph (11% identical), Caenorhabditis elegans pdp-1 (11% identical), and 5 more. Paralogues in human: PPM1F (15% identical), PPM1E (14% identical), PPM1H (14% identical), PPM1J (13% identical), PPM1L (13% identical), PPM1N (13% identical), PPM1M (12% identical), PPM1A (12% identical), PPM1B (12% identical), PDP1 (12% identical), PDP2 (11% identical), TAB1 (11% identical), and 4 more.